FAM209B (family with sequence similarity 209 member B)
Description:
May play a role in sperm acrosome biogenesis.
Synonyms: C20orf107; dJ1153D9.4
Tractability: Antibody: UniProt predicts a signal peptide or a membrane-spanning region.
Gene: Protein-coding gene on chromosome 20 (56,533,246 to 56,536,520, forward strand). Ensembl gene ENSG00000213714.
Subcellular location: Nucleus inner membrane; Cytoplasmic vesicle, secretory vesicle, acrosome
Gene Ontology:
Cellular component: acrosomal vesicle; nucleus; nuclear inner membrane
Genetic constraint (gnomAD): Loss-of-function variants: 11 observed, 9.93 expected, observed/expected ratio (o/e) 1.11, 90% interval 0.69 to 1.75. That is too few expected variants to judge how well the gene tolerates losing a copy. Missense variants: 168 observed, 201.29 expected, observed/expected ratio (o/e) 0.83, 90% interval 0.74 to 0.95. Synonymous variants: 65 observed, 74.29 expected, observed/expected ratio (o/e) 0.88, 90% interval 0.72 to 1.08.
Homologues: Orthologues: chimpanzee FAM209B (97% identical), pig FAM209B (64% identical), mouse Fam209 (59% identical), rat Fam209 (59% identical). Paralogues in human: FAM209A (88% identical).
Diseases named in the same sentence as FAM209B in open-access papers:
FAM209B is named in the same sentence as 8 diseases in open-access papers, as found by Europe PMC text mining. Sharing a sentence is not in itself a finding about the gene and the disease.
FAM209B shares sentences with these, for which no sentence is quoted: Alzheimer disease (1 paper); autoimmune disease (1); Huntington disease (1); Parkinson disease (1); rheumatoid arthritis (1); systemic lupus erythematosus (1); type 1 diabetes (1); viral myocarditis (1).